ZNF502 (zinc finger protein 502)
Description:
May be involved in transcriptional regulation.
Synonyms: FLJ14855; FLJ12515
Tractability: PROTAC: UniProt records ubiquitination sites on it; ubiquitination databases record sites on it.
Gene: Protein-coding gene on chromosome 3 (44,712,640 to 44,723,831, forward strand). Ensembl gene ENSG00000196653.
Subcellular location: Nucleus
Gene Ontology:
Molecular function: protein binding; DNA-binding transcription factor activity, RNA polymerase II-specific; RNA polymerase II cis-regulatory region sequence-specific DNA binding
Biological process: host-mediated activation of viral process; viral release from host cell; regulation of DNA-templated transcription; regulation of transcription by RNA polymerase II
Cellular component: nucleus
Genetic constraint (gnomAD): Loss-of-function variants: 29 observed, 46.6 expected, observed/expected ratio (o/e) 0.62, 90% interval 0.46 to 0.85. The synonymous counts are far from expectation, so gnomAD's model fits this gene poorly and the ratio says little. Missense variants: 591 observed, 683.28 expected, observed/expected ratio (o/e) 0.86, 90% interval 0.81 to 0.93. Synonymous variants: 171 observed, 219.3 expected, observed/expected ratio (o/e) 0.78, 90% interval 0.69 to 0.88.
Homologues: Orthologues: chimpanzee ZNF502 (99% identical), macaque ZNF502 (97% identical), dog ZNF502 (90% identical), pig ZNF502 (87% identical), rabbit ZNF502 (85% identical). Paralogues in human: ZNF7 (44% identical), ZNF658 (43% identical), ZNF708 (43% identical), ZNF595 (43% identical), ZNF717 (43% identical), ZNF726 (43% identical), ZNF724 (42% identical), ZNF728 (42% identical), ZNF33B (42% identical), ZNF250 (42% identical), ZNF254 (42% identical), ZNF484 (42% identical), and 164 more.
Diseases named in the same sentence as ZNF502 in open-access papers:
ZNF502 is named in the same sentence as 10 diseases in open-access papers, as found by Europe PMC text mining. Sharing a sentence is not in itself a finding about the gene and the disease. The quoted sentences say what the papers report.
depression (3 papers, 2021 to 2024). "It is possible that ZNF501/ZNF502 confer risk of depression by regulating gene expression." (PMID 34021117, 2021). "Seven out of 53 risk genes (B3GALTL, FADS1, TCTEX1D1, XPNPEP3, ZMAT2, ZNF501 and ZNF502) showed TWS associations with depression in two independent brain expression quantitative loci (eQTL) datasets, suggesting that these genes may represent promising candidates." (PMID 34021117, 2021). "The significant CpG for granulocytes (P = 3.10 × 10–9, q = 0.075) was intergenic but the significant CpG in NK cells overlapped with ZNF502 (P = 3.88 × 10–9, q = 0.094), a possible biomarker for depression." (PMID 38778395, 2024). "It is found that ZNF502 is related to acute myeloid leukemia, depression, and respiratory syncytial virus replication." (PMID 37902191, 2023).
acute myeloid leukemia (2 papers, 2023). Acute myeloid leukemia (AML) is a group of neoplasms arising from precursor cells committed to the myeloid cell-line differentiation. "Genome-wide differential gene/microRNA signatures show that ZNF502 might be a prognostic biomarker in cytogenetically normal acute myeloid leukemia." (PMID 37013470, 2023).
schizophrenia (2 papers, 2021 to 2023). A major psychotic disorder characterized by abnormalities in the perception or expression of reality. "To explore if expression of ZNF501, ZNF502, B3GALTL were associated with schizophrenia and bipolar disorder, we further examined TWAS results of these three genes (i.e. ZNF501, ZNF502 and B3GALTL) in PsychENCODE24." (PMID 34021117, 2021).
esophageal cancer (1 paper, 2023). A primary or metastatic malignant neoplasm involving the esophagus. "In our study, the expression of ZNF502 is low in esophageal carcinoma, which is associated with poor prognosis." (PMID 37013470, 2023). "Results indicate that ZNF91, and ZNF586 were upregulated in esophageal cancer tissue than adjacent tissue, whereas ZNF502, ZNF865, ZNF106, and ZNF225 was downregulated." (PMID 37013470, 2023).
cancer (2 papers, 2021 to 2023). A tumor composed of atypical neoplastic, often pleomorphic cells that invade other tissues. "The distribution of the degree of methylation indicated that in the normal lung tissue group, ZNF518B and ZNF502 presented a hypomethylated state, while in the EAC cancer group, ZNF518B and ZNF502 presented a hypermethylated state." (PMID 34222478, 2021).
psychiatric disorder (1 paper, 2023). A disorder characterized by behavioral and/or psychological abnormalities, often accompanied by physical symptoms. "ZNF502 was unique to SD, but the other five genes overlapped with the results from other psychiatric disorders above." (PMID 37794117, 2023).
ZNF502 also shares sentences with these, for which no sentence is quoted: autism (1 paper); bipolar disorder (1); oral squamous cell carcinoma (1); tumor (1).